CBFB (core-binding factor subunit beta)
Description:
Forms the heterodimeric complex core-binding factor (CBF) with RUNX family proteins (RUNX1, RUNX2, and RUNX3). RUNX members modulate the transcription of their target genes through recognizing the core consensus binding sequence 5'-TGTGGT-3', or very rarely, 5'-TGCGGT-3', within their regulatory regions via their runt domain, while CBFB is a non-DNA-binding regulatory subunit that allosterically enhances the sequence-specific DNA-binding capacity of RUNX. The heterodimers bind to the core site of a number of enhancers and promoters, including murine leukemia virus, polyomavirus enhancer, T-cell receptor enhancers, LCK, IL3 and GM-CSF promoters. CBF complexes repress ZBTB7B transcription factor during cytotoxic (CD8+) T cell development. They bind to RUNX-binding sequence within the ZBTB7B locus acting as transcriptional silencer and allowing for cytotoxic T cell differentiation. (Microbial infection) Following infection, hijacked by the HIV-1 Vif protein, leading to the formation a cullin-5-RING E3 ubiquitin-protein ligase complex (ECS complex) that catalyzes ubiquitination and degradation of APOBEC3F and APOBEC3G. The complex can also ubiquitinate APOBEC3H to some extent. Association with HIV-1 Vif protein also inhibits the transcription coactivator activity of CBFB/CBF-beta.
Synonyms: PEBP2B; CLCD2
Tractability: Small molecule: a structure with a bound ligand is known; a high-quality ligand is known. PROTAC: ubiquitination databases record sites on it; its protein half-life has been measured; a small molecule that binds it is known.
Gene: Protein-coding gene on chromosome 16 (67,028,984 to 67,101,058, forward strand). Ensembl gene ENSG00000067955.
Subcellular location: Nucleus
Subcellular location (Human Protein Atlas): Cytosol; Nucleoplasm
Pathways (Reactome):
Gene expression (Transcription): RUNX1 and FOXP3 control the development of regulatory T lymphocytes (Tregs); RUNX1 interacts with co-factors whose precise effect on RUNX1 targets is not known; RUNX1 regulates estrogen receptor mediated transcription; RUNX1 regulates expression of components of tight junctions; RUNX1 regulates genes involved in megakaryocyte differentiation and platelet function; RUNX1 regulates transcription of genes involved in BCR signaling; RUNX1 regulates transcription of genes involved in WNT signaling; RUNX1 regulates transcription of genes involved in differentiation of HSCs; RUNX1 regulates transcription of genes involved in differentiation of keratinocytes; RUNX1 regulates transcription of genes involved in differentiation of myeloid cells; RUNX1 regulates transcription of genes involved in interleukin signaling; RUNX2 regulates bone development; RUNX2 regulates chondrocyte maturation; RUNX2 regulates genes involved in cell migration; RUNX2 regulates genes involved in differentiation of myeloid cells; RUNX2 regulates osteoblast differentiation; RUNX3 Regulates Immune Response and Cell Migration; RUNX3 regulates RUNX1-mediated transcription; RUNX3 regulates p14-ARF; Regulation of RUNX1 Expression and Activity; Regulation of RUNX2 expression and activity; Regulation of RUNX3 expression and activity; Transcriptional regulation by RUNX2
Developmental Biology: Transcriptional regulation of granulopoiesis
Signal Transduction: Estrogen-dependent gene expression
Gene Ontology:
Molecular function: protein binding; sequence-specific DNA binding; transcription coactivator activity; DNA binding
Biological process: protein polyubiquitination; regulation of transcription by RNA polymerase II; negative regulation of CD4-positive, alpha-beta T cell differentiation; negative regulation of transcription by RNA polymerase II; positive regulation of CD8-positive, alpha-beta T cell differentiation; transcription by RNA polymerase II; positive regulation of DNA-templated transcription; regulation of DNA-templated transcription
Cellular component: core-binding factor complex; membrane; nucleoplasm; nucleus
Genetic constraint (gnomAD): Loss-of-function variants: 4 observed, 8.59 expected, observed/expected ratio (o/e) 0.47, 90% interval 0.23 to 1.07. That is too few expected variants to judge how well the gene tolerates losing a copy. Missense variants: 82 observed, 95.37 expected, observed/expected ratio (o/e) 0.86, 90% interval 0.72 to 1.03. Synonymous variants: 48 observed, 33.48 expected, observed/expected ratio (o/e) 1.43, 90% interval 1.14 to 1.8.
Gene-disease validity (ClinGen):
ClinGen rates the evidence that CBFB causes each of these diseases.
cleidocranial dysplasia 2 (autosomal dominant): Definitive.
Cancer hallmarks: invasion and metastasis (promotes)
Homologues: Orthologues: dog CBFB (100% identical), macaque CBFB (100% identical), mouse Cbfb (99% identical), chimpanzee CBFB (90% identical), pig CBFB (90% identical), tropical clawed frog cbfb (89% identical), rat Cbfb (89% identical), zebrafish cbfb (87% identical), Drosophila melanogaster Bgb (50% identical), Drosophila melanogaster Bro (46% identical), Caenorhabditis elegans bro-1 (21% identical).
Diseases named in the same sentence as CBFB in open-access papers:
CBFB is named in the same sentence as 89 diseases in open-access papers, as found by Europe PMC text mining. Sharing a sentence is not in itself a finding about the gene and the disease. The quoted sentences say what the papers report.
acute myeloid leukemia (53 papers, 2009 to 2026). Acute myeloid leukemia (AML) is a group of neoplasms arising from precursor cells committed to the myeloid cell-line differentiation. "Patient 4 (P4) F/58Y and 5 (P5) F/66Y were acute myeloid leukaemia (AML) patients with rare CBFB::MYH11 Type G and I fusion transcripts respectively." (PMID 38493200, 2024). "The core binding factor (CBF) protein complex, composed of RUNX1 and CBFB, is important for myeloid differentiation and recurrently altered in acute myeloid leukemia (AML) through genomic rearrangements." (PMID 31896782, 2020). "In some cases of acute myeloid leukemia, CBFβ is fused to the smooth muscle myosin protein, favoring formation of the CBFβ-Runx1 complex and resulting in dysfunction in CBF transcription." (PMID 26380257, 2015). "For some of the TFs not previously reported to be deregulated in CRC, the involvement in the tumorigenesis of other cancers has been well established for example, SOX4 in bladder cancer and CBFB in acute myeloid leukaemia." (PMID 19156145, 2009). "Both RUNX1 and CBFB undergo chromosomal rearrangements in acute myeloid leukemia (AML)." (PMID 25612891, 2015). "Furthermore, oncogenic rearrangements of RUNX1 and/or CBFB are common in acute myeloid leukemia (AML)." (PMID 26561834, 2015). "We report a unique pediatric acute myeloid leukemia (AML) case characterized by a CBFB::MYH11 fusion located on a supernumerary ring chromosome 16." (PMID 41300735, 2025). "Core binding factor acute myeloid leukemia (CBF-AML) includes AML cases harboring RUNX1::RUNX1T1 or CBFβ::MYH11 fusion genes, which are classified as a favorable-risk group." (PMID 38802593, 2024). "In this study, we performed an integrated analysis of bulk and single-cell DNA sequencing data of core-binding factor acute myeloid leukemia patients, defined by the presence of a RUNX1::RUNX1T1 or CBFB::MYH11 fusion gene." (PMID 41152985, 2025). "In acute myeloid leukemia (AML), CBFB is one of the most targeted genes, with most of the genetic alterations being fusions, such as to the MYH11 gene." (PMID 33945523, 2021). "The fusion genes CBFB/MYH11 and RUNX1/RUNX1T1 block differentiation through disruption of the core binding factor (CBF) complex and are found in 10–15% of adult de novo acute myeloid leukemia (AML) cases." (PMID 31896782, 2020). "In acute myeloid leukemia (LAML), several CBFB fusions but no mutations were observed, yet other cancer types also exhibited CBFB mutations." (PMID 29617662, 2018). "Additionally, conditions such as acute myeloid leukemia (AML) with RUNX1::RUNX1T1 fusion, AML with CBFB::MYH11 fusion, myeloid/lymphoid neoplasms with eosinophilia and specific gene rearrangements, and the blast phase of chronic myeloid leukemia (CML) must be excluded from the diagnosis." (PMID 41366999, 2025).
breast carcinoma (43 papers, 2010 to 2026). "We next investigated the applicability of our results to human cancer by comparing our DEG analyses in mouse MC38 and E0771 cancer cells to a published RNA-seq dataset from wildtype and CBFβ deficient human breast cancer cells (MCF10A)." (PMID 39261596, 2024). "While RUNX1 and CBFβ have been most widely studied in the context of blood cancers, they have over the last decade been implicated in breast cancers, both in the context of tumor suppression and tumor promotion." (PMID 36831308, 2023). "Abnormal expression of CBFB is associated with blood cancers, breast cancer, colorectal cancer and gastric cancer." (PMID 35428233, 2022). "Increased CBFB expression was associated with metastasis and poor prognosis in patients with breast cancer." (PMID 35903297, 2022). "We used the gain-of-function and loss-of-function approaches to investigate the role of CBFB in the evasion of cellular stress and apoptosis and in breast cancer cell metastasis." (PMID 35903297, 2022). "To further explore the tumor suppressive function of CBFB in breast cancer, we calculated the genetic interaction (epistasis) of the mutations of two cancer genes in breast cancer." (PMID 33945523, 2021). "The CBFB gene, which encodes a transcription factor, has recently emerged as a highly mutated driver in a variety of human cancers including breast cancer." (PMID 31061501, 2019). "CBFB is highly mutated in breast cancers and is known to interact with RUNX proteins to regulate transcription." (PMID 31061501, 2019). "This site was mutated in at least 1.5% of ER+ breast cancers sequenced, bringing the overall rate of CBFB mutations to nearly 6%, which should drive further investigation of this gene in ER+ breast cancer pathogenesis." (PMID 30181556, 2018). "Recurrent mutations in RUNX1 and its binding partner CBFβ were detected in two independent cohorts of breast cancer deep sequencing studies." (PMID 29581836, 2018). "We show that CBFβ is expressed in the metastatic breast cancer cells, MDA-MB-231, and that it associates with Runx2." (PMID 20591170, 2010). "Further examination of this co-occurring mutation across all cancer studies on cBioPortal showed that this mutational relationship between DDR1 and either RUNX1 or CBFβ remained strongly significant, indicating that this axis is worth investigating outside of breast cancer." (PMID 40614729, 2025). "Current evidence indicates that RUNX1 and CBFβ are among the 30 most frequently mutated genes in breast cancer, with a prevalence of approximately 4%–5% in breast cancer cases." (PMID 40614729, 2025).
breast carcinoma (continued). "Both RUNX1 and CBFβ are in the top 30 genes mutated in breast cancer." (PMID 40614729, 2025). "RUNX1 and CBFB loss-of-function mutations are strongly associated with ER+ breast cancer." (PMID 36831308, 2023). "CBFB (Core-binding factor subunit beta) gene encodes a transcription factor that has emerged as a highly mutated driver in a variety of human cancers including breast cancer." (PMID 37187521, 2023). "Interestingly, The Cancer Genome Atlas (TCGA) PanCancer Atlas shows that a significant percentage of all breast cancer cases are linked to alterations in the genes encoding the RUNX/CBFβ complex." (PMID 36831308, 2023). "Notably, we provide evidence that CBFB is implicated in breast cancer metastasis to the bones and that this is associated with the exosomal enrichment of CBFB in the serum of patients with breast cancer." (PMID 35903297, 2022). "Increased CBFB activity has been associated with increased breast cancer invasiveness." (PMID 35903297, 2022). "Finally, we demonstrate that loss of CBFβ inhibits the ability of metastatic breast cancer cells to invade bone cell cultures and suppresses their ability to form bone metastases in vivo." (PMID 32005976, 2020). "Finally, we demonstrate that loss of CBFβ, inhibits the ability of metastatic breast cancer cells to colonise osteoblasts in long-term 3D cultures." (PMID 32005976, 2020). "Moreover, mutations in RUNX1 and CBFβ are associated with the ER+ sub-type of breast cancer and is therefore predicted to have a tumour suppressor role in this context." (PMID 32005976, 2020). "Thus, more detailed studies are needed to establish whether CBFB function is linked to subtype of breast cancer." (PMID 31061501, 2019). "However, CBFβ mutations may be under reported, as deletion of its chromosomal loci at 16q22 represents one of the most frequent and earliest genomic alterations observed in breast cancer, affecting roughly 50% of all cases." (PMID 40614729, 2025). "Recently, RUNX1 and CBFβ have all garnered attention as potential clinical targets in breast cancer." (PMID 40614729, 2025). "Mendoza-Villanueva and colleagues have shown that Runx2 and CBFb inhibit osteoblast differentiation in bone metastatic breast cancer cells and that this inhibition is mediated by the induction of sclerostin expression." (PMID 38247829, 2024). "Runx2 requires co-activator core-binding factor beta (CBFb) to regulate gene expression in breast cancer cells." (PMID 38247829, 2024). "According to the METABRIC study, elevated expression of CBFB has been observed in 3% of breast cancer patients although, notably, gene amplification and high expression of mRNA were predominately in ER-negative patient samples." (PMID 36831308, 2023). "Considering how strongly RUNX/CBFβ-mediated effects are correlated with the ER status of breast cancers, it is obvious that a complicated relationship (either direct or indirect, if not both) exists between the ER and the RUNX/CBFβ heterodimeric complex." (PMID 36831308, 2023). "It is evident that the RUNX/CBFβ transcriptional complex has an important role in breast cancer biology and in normal mammary epithelial development, not least through its intricate relationship with ER/estrogen signaling." (PMID 36831308, 2023). "High expression of CBFβ, and a consequent increase in tumor cell invasiveness and migratory potential, has been demonstrated in two further metastatic breast cancer cell lines." (PMID 36831308, 2023). "CBFB expression was the highest in breast cancer cell lines derived from brain and skin metastatic sites." (PMID 35903297, 2022).